TREH (trehalase)
Description:
Intestinal trehalase is probably involved in the hydrolysis of ingested trehalose.
Synonyms: TREA; TRE; MGC129621; TREHD
Tractability: Antibody: its Gene Ontology location is reachable by antibodies, with high confidence; UniProt places it where antibodies can reach, with medium confidence; UniProt predicts a signal peptide or a membrane-spanning region. PROTAC: a small molecule that binds it is known.
Target class: Enzyme; Hydrolase
Gene: Protein-coding gene on chromosome 11 (118,657,316 to 118,679,690, reverse strand). Ensembl gene ENSG00000118094.
Subcellular location: Cell membrane
Subcellular location (Human Protein Atlas): Cytosol; Vesicles
Pathways (Reactome):
Digestion and absorption: Digestion of dietary carbohydrate
Gene Ontology:
Molecular function: alpha,alpha-trehalase activity
Biological process: trehalose catabolic process; trehalose metabolic process; animal organ morphogenesis; carbohydrate metabolic process
Cellular component: extracellular exosome; membrane; plasma membrane
Genetic constraint (gnomAD): Loss-of-function variants: 70 observed, 71.79 expected, observed/expected ratio (o/e) 0.98, 90% interval 0.8 to 1.19. The upper end of that interval is the gene's LOEUF score, 1.19, which puts it in group 5 of 6, group 1 being the genes least tolerant of losing a copy. Missense variants: 716 observed, 668.85 expected, observed/expected ratio (o/e) 1.07, 90% interval 1.01 to 1.14. Synonymous variants: 309 observed, 268.49 expected, observed/expected ratio (o/e) 1.15, 90% interval 1.05 to 1.26.
Homologues: Orthologues: chimpanzee TREH (99% identical), macaque TREH (97% identical), rabbit TREH (81% identical), mouse Treh (81% identical), rat Treh (81% identical), pig TREH (81% identical), guinea pig TREH (81% identical), dog TREH (77% identical), tropical clawed frog treh (52% identical), zebrafish treh (51% identical), Drosophila melanogaster Treh (42% identical), Caenorhabditis elegans tre-3 (40% identical), and 5 more.
Diseases named in the same sentence as TREH in open-access papers:
TREH is named in the same sentence as 30 diseases in open-access papers, as found by Europe PMC text mining. Sharing a sentence is not in itself a finding about the gene and the disease. The quoted sentences say what the papers report.
diabetes (6 papers, 2013 to 2025). "It is interesting to note that a recent human genetics study described single nucleotide polymorphisms in the trehalase gene (TREH), which resulted in lower levels of trehalase activity and lower diabetes risk in Pima Indians39." (PMID 28589926, 2017). "However, there was otherwise little correspondence between the effect of a haplotype on trehalase activity and diabetes risk." (PMID 23468175, 2013). "Thus, linkage analysis in the present set of families has limited power to resolve the extent of overlap between variants affecting trehalase levels and diabetes risk, and further association studies were conducted." (PMID 23468175, 2013). "In diabetes, higher trehalase activity and genetic variations in the trehalase gene were noted." (PMID 29907758, 2018). "Although all individuals were nondiabetic at the examination for which trehalase activity was measured, 320 had been subsequently examined in the longitudinal study and 214 had developed diabetes." (PMID 23468175, 2013). "Among these individuals trehalase activity did not significantly predict development of diabetes (hazard ratio 0.93 per SD increase in trehalase activity, 95 % CI 0.81–1.07, p = 0.29)." (PMID 23468175, 2013). "However, among 320 longitudinally studied subjects, measures of trehalase activity from a non-diabetic exam did not predict those who would eventually develop diabetes versus those who would remain non-diabetic (hazard ratio 0.94 per SD of trehalase activity, p = 0.29)." (PMID 23468175, 2013). "HES antigens treated with trehalase, which degrades trehalose, did not induce CD8+ Treg cells or suppress diabetes." (PMID 32321922, 2020).
type 2 diabetes (4 papers, 2013 to 2025). "It is crucial in regulating trehalase activity, which is closely associated with type 2 diabetes and BMI among Filipino women." (PMID 39194753, 2024). "Furthermore, it was recently reported that genetic variants in or near the TREH locus in Pima Indians are strongly associated with trehalase activity, and one of these variants is also reproducibly associated with type 2 diabetes." (PMID 40529415, 2025). "Additionally, similar to PAI-1, TREH is a stress response gene known to associate with susceptibility to Type 2 diabetes." (PMID 26322636, 2015).
fungal infections (3 papers, 2020 to 2023). "Validamycin A, which is a trehalase inhibitor, has been used to prevent fungal infections of agricultural products." (PMID 38005693, 2023). "Validamycin A, a well-known trehalase inhibitor, is already used in food crops to prevent fungal infections." (PMID 33356857, 2021). "Trehalase is an essential enzyme involved in fungal metabolism, and the trehalase inhibitor, validamycin A, has been used to prevent fungal infections in agricultural products." (PMID 32676114, 2020).
Hypoglycemia (2 papers, 2018 to 2025). A decreased concentration of glucose in the blood. "Injecting 50 μg of the trehalase inhibitor trehazolin into locusts (L. migratoria) resulted in 50% insect mortality after 24 h, likely because of severe hypoglycemia." (PMID 40265736, 2025). "Injection of these neurohormones induced a strong, dose-dependent hypoglycemia and increased the activity of trehalase in the midgut and muscles." (PMID 30577556, 2018).
malaria (2 papers, 2022 to 2023). Malaria is a serious and sometimes fatal disease caused by a parasite that commonly infects a certain type of mosquito which feeds on humans. "One of the targets identified for malaria drug design is trehalase, an enzyme responsible for reducing trehalose, resulting in two glucose molecules." (PMID 37298256, 2023). "Moreover, trehalase has become an attractive target for malaria vectors due to its specificity towards insects, deeming it safe for human consumption." (PMID 37298256, 2023). "This study screened trehalase inhibitors against AgTre to identify inhibitors with better affinity than validamycin A, which could be developed further for malaria vector control." (PMID 36421973, 2022). "gambiae trehalase (AgTre) was determined and molecular docking was employed to screen a library of compounds in order to identify potential lead structures against AgTre that could be developed for malaria vector control." (PMID 36421973, 2022). "Since trehalase from both organisms share >70% sequence identity, inhibitors could be used to control both vectors, preventing transmission of other mosquito-borne diseases aside from malaria, e.g., dengue fever." (PMID 36421973, 2022).
Obesity (2 papers, 2020 to 2025). Accumulation of substantial excess body fat. "Our findings that an oral route of trehalose administration as well as inhibition of trehalase are ineffective in mitigating diet-induced obesity and metabolic disease should provide clarity for the field." (PMID 40529415, 2025). "In the current study, we aimed to definitively study the efficacy of trehalose in obesity and metabolic disease while taking into account both the route of administration and the oft neglected role for trehalase." (PMID 40529415, 2025).
atherosclerosis (1 paper, 2017). A disease characterized by the build-up of fatty material and calcium deposition in the arterial wall resulting in partial or complete occlusion of the arterial lumen. "This can be directly tested by determining whether oral trehalose absorption can be augmented and lead to lower atherosclerosis in trehalase-deficient mice." (PMID 28589926, 2017).
cardiomyopathy disease (1 paper, 2015). "Trehalase can become a possible marker of intestinal ischemia-reperfusion injury because of its release, binding, and perfusion inside cardiac muscles that display cardiomyopathy disease." (PMID 25949827, 2015).
mastitis (1 paper, 2024). Inflammation of breast tissue during lactation or postpartum due to an obstructed duct or infection. "Three Gram type-specific LAMP assays to detect DNA of the majority of bovine mastitis causing bacteria were developed to be compatible with the conditional complementation of split-trehalase recombinant proteins fused to the DNA binding protein SpoIIID." (PMID 38887539, 2024). "A novel strategy for the detection of mastitis causative pathogens in milk samples involves combining the split trehalase biosensing platform with DNA-binding protein specificity and LAMP amplicons containing protein-binding sites." (PMID 38887539, 2024). "Here, a novel diagnostic method was developed to detect mastitis pathogens in milk samples by combining loop-mediated isothermal amplification with a split enzyme biosensor whereby trehalase fragments were fused with a DNA-binding protein, SpoIIID." (PMID 38887539, 2024). "High specificity of the three derived LAMP assays were demonstrated by amplifying gDNA from ten common isolates from both Gram-types of mastitis bacteria with expected signals originating from the restoration of trehalase activity by ABSTA." (PMID 38887539, 2024).
melanoma (1 paper, 2022). A malignant, usually aggressive tumor composed of atypical, neoplastic melanocytes. "The present study investigated the antimelanogenic effects of miglitol and the trehalase inhibitor validamycin A. Miglitol in isolation exhibited no cytotoxicity and significantly reduced the melanin production and intracellular tyrosinase activity in B16F10 melanoma cells." (PMID 36615308, 2022).
proteinopathy (1 paper, 2024). "Although trehalose is considered safe, we included the trehalase-resistant analog lactotrehalose in our analysis to assess its ability to restore autophagy and inhibit proteinopathy." (PMID 38760513, 2024).
spinocerebellar ataxia (1 paper, 2020). "Its trehalase-indigestible analogs, lactulose and melibiose, also demonstrated potentials to reduce abnormal protein aggregation in spinocerebellar ataxia cell models." (PMID 32429337, 2020).
infection (15 papers, 2012 to 2025). The state of being infected such as from the introduction of a foreign agent such as serum, vaccine, antigenic substance or organism. "In CNs, a secreted trehalase (encoded by Hsc_gene_15468) has been identified as a virulence effector candidate, produced in subventral gland cells, and is likely secreted into the apoplast during the early stages of infection." (PMID 40737394, 2025). "This conservation highlights the significance of trehalase, a trehalose-degrading enzyme, as a crucial factor for diverse pathogens using distinct infection strategies." (PMID 40737394, 2025). "The enzymatic activities of the carbohydrate hydrolyzing enzymes, namely invertase and trehalase were assessed as a biochemical indicator of the honeybee’s utilization efficiency of the ingested sugars, at 9 days post infection." (PMID 39550385, 2024). "Here, we review studies that reveal the importance of dietary and stored nutrients during mosquito development and infection and suggest strategies to identify next-generation insecticides with a focus on trehalase inhibitors." (PMID 36851683, 2023). "Further, we discuss how these same nutrients impact infection with important vector-borne diseases and focus on the development of trehalase inhibitors as a future direction." (PMID 36851683, 2023). "In M. oryzae, both the synthesis of trehalose by a trehalose-6-phosphate synthase and the breakdown of trehalose by trehalase were shown to play a role in the infection of rice." (PMID 34686023, 2021). "The synthase was shown to be required for appressorium-mediated penetration and the trehalase for the development of infection after penetration." (PMID 34686023, 2021). "In addition, a parasite aspartyl protease inhibitor and several effectors related to environmental resistance such as superoxide dismutase (SOD), and trehalase also help worms defend against Bt infection." (PMID 35773333, 2022). "In order to investigate whether the trehalase enzymes are involved in C. glabrata virulence in a systemic infection, mice were infected intravenously with the different deletion strains." (PMID 33356857, 2021). "Interestingly, later during infection (12–18 hpi), the circulating hemocytes together with already differentiated lamellocytes strongly increased expression of both Tret1-1 and trehalase (CG9364; FlyBase ID: FBgn0003748)." (PMID 25915062, 2015). "Conceptually, infection with Xcc might increase the level of trehalose by inducing the plant’s own trehalose biosynthetic pathway or repressing its trehalase activity." (PMID 25770587, 2015). "The gene encoding neutral trehalase (Ar25) showed no significant change in expression during infection, which supports the finding that the M. oryzae trehalase, TRE1 did not play a significant role in pathogenesis." (PMID 22427966, 2012). "However, the tomato host produces the trehalose in xylem sap during infection; R. solanacearum does not export its trehalose in culture and it aggressively expresses the secreted trehalase TreA in planta." (PMID 35476629, 2022).
neurodegenerative disease (2 papers, 2020). A disorder of the central nervous system characterized by gradual and progressive loss of neural tissue and neurologic function. "It is important to note that trehalose is readily digested by trehalase in the gut of humans, which implicates trehalase-indigestible analogs rather than trehalose as the potential treatments for aggregation-associated neurodegenerative disease." (PMID 32848705, 2020). "It is important to note that trehalose is readily digested by trehalase in the gut of humans, which implicates trehalase-indigestible analogs rather than trehalose as the potential treatments for aggregation-associated neurodegenerative diseases." (PMID 32429337, 2020). "However, trehalose is rapidly hydrolyzed in the intestine to glucose by trehalase, limiting its therapeutic application for neurodegenerative diseases." (PMID 32429337, 2020).
tumor (1 paper, 2026). "The loss of TREH is associated with tumor progression and correlates with EMT activation and a pro-angiogenic microenvironment, suggesting its potential as a therapeutic target for improving patient outcomes." (PMID 42200006, 2026). "Mechanistically, our data suggest that TREH acts as a tumor suppressor." (PMID 42200006, 2026).
TREH also shares sentences with these, for which no sentence is quoted: asthma (1 paper); COVID-19 (1); dengue fever (1); fucosidosis (1); Hepatic steatosis (1); Huntington disease (1); lysosomal storage disorders (1); malnutrition (1); metabolic disease (1); muscular dystrophy (1); nematode infections (1); Parkinson’s (1); prion disease (1); Sepsis (1); urinary tract infection (1).